CRP (C-reactive protein)
Diseases named in the same sentence as CRP in open-access papers (continued):
Sharing a sentence is not in itself a finding about the gene and the disease.
Insulin resistance (continued). "Participants with insulin resistance, dyslipidemia, and MetS exhibited significantly higher CRP concentrations than individuals without these conditions." (PMID 39452916, 2024). "Similarly, the IAPPO-IgA levels correlated positively with the metabolic markers glucose, glucagon, and GIP, as well as with inflammatory total IgA, CRP, and GGT, and the change in IAPPO-IgA levels correlated positively with the change in insulin resistance." (PMID 39062913, 2024). "In addition, C-reactive protein (CRP) (p < 0.001), homeostasis model assessment–insulin resistance (HOMA-IR) (p < 0.05), and fasting blood glucose (p < 0.01) were elevated whilst PCOS women had a lower SHBG (p < 0.001)." (PMID 39858399, 2024). "ALT: alanine aminotransferase; AST: aspartate aminotransferase; CRP: C-reactive protein; BMI: body mass index; HbA1c: hemoglobin A1c; HOMA-IR: homeostasis model assessment—insulin resistance; PKU: phenylketonuria; SD: standard deviation; SMM: lean muscle mass; WHR: waist-to-hip ratio." (PMID 39408322, 2024). "Neither cognition nor mood was associated with fasting glucose levels, HbA1c, insulin resistance indices (HOMA IR, Matsuda indices), triglyceride, HDL, LDL, and/or CRP levels." (PMID 39121088, 2024). "PTSD is associated with elevated levels of inflammatory markers, including CRP, interleukin-6 (IL-6), and tumor necrosis factor-alpha (TNF-α), that could exacerbate insulin resistance." (PMID 38646205, 2024). "The C-reactive protein (CRP)-triglyceride-glucose (TyG) index (CTI), which is a measure representing the level of inflammation and insulin resistance (IR), is related to poor cancer prognosis; however, the CTI has not been validated in patients with cancer cachexia." (PMID 38273418, 2024). "Metabolic parameters, including blood glucose, Homeostasis Model Assessment of Insulin Resistance (HOMA-IR), Triglyceride/Glucose (TyG) index, and high-sensitivity C-reactive protein (hs-CRP), were assessed at discharge and followed up after 4 months (T4) and 12 months (T12)." (PMID 39595206, 2024). "Plasma substrates and hormones (glucose, insulin, and plasma lipids), markers of inflammation (C-reactive protein [CRP] and ferritin), and the homeostasis model assessment of insulin resistance (HOMA-IR) score did not change after orange supplementation." (PMID 39339791, 2024). "Additionally, 4 weeks of HIIT can decrease the F/B ratio in insulin-resistant patients, reduce serum levels of TNF-α, C-reactive protein (CRP), and lipopolysaccharide-binding protein (LBP), improving systemic insulin resistance." (PMID 39834360, 2024). "In the present study, we measured serum TRY, TRYCATs, insulin resistance (using the Homeostatic Model Assessment Index 2-insulin resistance, HOMA2-IR), C-reactive protein (CRP), physiosomatic, depression, and anxiety symptoms in 90 Long COVID patients, 3–10 months after remission of acute infection." (PMID 37333619, 2023). "There is a lack of longitudinal data regarding CRP and measures of hepatic and overall insulin resistance in women with GDM." (PMID 37891561, 2023). "In the combined analysis of the anthropometry, lipid and glucose profiles, inflammation markers, and the mean of the CIMT measurements, the WHtR, SAA, us-CRP, HOMA-IR, and insulin resistance had the highest discriminatory power between the overweight and eutrophic groups (AUC>0.7)." (PMID 37341220, 2023). "Despite the inter-relationship between IL-6, TNF-α and CRP, this study neither found similar associations between IL-6 and TNF-α with insulin resistance nor with other metabolic outcomes." (PMID 37891561, 2023). "CRP is stimulated by IL-1β, TNF-α and IL-6 in the liver, which act together to activate serine and threonine kinases to suppress insulin signal transduction and thus promote insulin resistance." (PMID 37891561, 2023). "Human recombinant CRP may increase IRS-1 phosphorylation through JNK and ERK1/2, leading to insulin resistance and increased glucose uptake." (PMID 37893085, 2023).
Insulin resistance (continued). "On the other side, serum LPC was decreased by elevated inflammatory status, such as insulin resistance, nonalcoholic steatohepatitis (NASH), and cancer-involved inflammation, where negative correlations were found between LPC and inflammatory markers (CRP and TNF-α)." (PMID 36989310, 2023). "Third, the study did not evaluate C-reactive protein, waist circumference, and insulin resistance, therefore, the prevalence of MAFLD is underestimated." (PMID 36604612, 2023). "The prediction of absolute insulin secretion by CRP is most likely related to the observed increase in insulin resistance, which was independent of weight and partly of body fat." (PMID 37891561, 2023). "In addition, CRP in the perinatal period predicted higher absolute insulin secretion (AUCins/glu, HOMA-B), but lower insulin resistance-adjusted insulin secretion (ISS1-2) at 1 year." (PMID 37891561, 2023). "For the two proteins that differed in women with PCOS versus control women (complement C3 and alpha-1-antitrypsin), correlations with age, BMI, insulin resistance (HOMA-IR), testosterone and circulating levels of TG, cholesterol, HDL-C, LDL-C and CRP were performed." (PMID 37181037, 2023). "↓FBG, serum insulin, CRP, and MDA; ↑TAC and GSH; and improved insulin resistance scores." (PMID 35052633, 2022). "The amelioration of insulin resistance was claimed under the mechanism of regulating intestinal flora to reduce tumor necrosis factor-α (TNF-α), interleukin-6 (IL-6), and hypersensitive C-reactive protein (HS-CRP) in plasma." (PMID 35529925, 2022). "A proinflammatory diet might contribute to the risk of T2D by elevating circulating levels of inflammatory cytokines (e.g., interferon γ, IL-1, IL-6, IL-8, CRP, and TNF-α), which can lead to insulin resistance." (PMID 35685508, 2022). "We assessed the prevalence of the metabolically healthy obese (MHO) phenotype and its relationship with high sensitivity C-reactive protein (hs-CRP), serum alanine aminotransferase (ALT), and insulin resistance (HOMA-IR) in Arab and South Asian ethnic groups in Kuwait." (PMID 35267891, 2022). "Third, we had no available data on CRP, insulin resistance, and inflammatory parameters such as tumor necrosis factor and IL-6, since they were not routinely measured." (PMID 35572991, 2022). "For women with an uncomplicated index pregnancy, those who were obese had significantly higher serum insulin, insulin resistance, and CRP levels than women who were not obese in early pregnancy." (PMID 35817936, 2022). "The implant does not exert a negative effect on cardiovascular risk factors (such as C-reactive protein (CRP), cholesterol/HDL ratio) nor on carbohydrate metabolism; furthermore, its use is related to lower risk of insulin resistance and dyslipidemia." (PMID 34201123, 2021). "Combined exenatide and metformin showed better effects on female than male patients for improving insulin sensitivity and serum lipid profile, reducing insulin resistance, increasing adiponectin levels, and decreasing the levels of HbA1c, BMI, resistin, TNF-alpha, CRP (p<0.05)." (PMID 34367059, 2021). "In addition to weight loss in obese or overweight women, caloric restriction reduces leptin, total C-reactive protein (CRP), LDL-cholesterol, triglycerides, blood pressure, fasting insulin and insulin resistance." (PMID 34660673, 2021). "Intermittent hypoxia and insulin resistance in OSAHS patients can promote the increase of inflammatory markers, including nitric oxide (NO), endothelin-1(ET-1), interleukin-6 (IL-6), and C-reactive protein (CRP)." (PMID 33628835, 2021). "The roles of IL-6, TNF- α, CRP, and IGF-1 in insulin resistance have been widely studied." (PMID 33432036, 2021). "Variables of body composition (BMI, waist to hip ratio) and insulin resistance were correlated with CRP or IL-6, while parameters of hyperandogenism were not." (PMID 33849511, 2021).
Insulin resistance (continued). "With increase in EAT thickness, the levels of CRP, IL-6, visfatin, and JAZF1 also increase, which can induce hyperglycemia, insulin resistance, and vascular endothelial dysfunction, etc., promoting the occurrence and development of atherosclerosis, leading to macroangiopathy." (PMID 33722242, 2021). "Secondly, we do not detect the level of insulin resistance and C-reactive protein, which are the components of metabolic disorders for the definition of MAFLD." (PMID 34496912, 2021). "In both populations, PCOS women showed a worse cardiovascular risk profile of increased systolic and diastolic blood pressure, increased C-reactive protein (CRP), reduced HDL, insulin resistance as well as increased androgens compared to their respective controls without PCOS." (PMID 33144665, 2020). "Moreover, in hepatocytes these cytokines stimulate the release of acute-phase protein, CRP (C-reactive protein), whereas TNFα, IL6 and CRP can, in turn, provoke insulin-resistance in target cells such as the endothelium." (PMID 32408603, 2020). "The term metabolic inflammation is also increasingly used to explain emerging insulin resistance and links the observations that are made with regards to increasing levels of fasting insulin, decreasing adiponectin, elevated PAI-1 and CRP—all findings aligned with the elevated levels of endotoxin." (PMID 32151020, 2020). "Higher circulating C-reactive protein, interleukin 6, and tumor necrosis factor alpha have been reported in PCOS which, through various mechanisms, can contribute to adipocyte dysfunction, insulin resistance, and type 2 diabetes." (PMID 31952348, 2020). "Taurine supplementation normalized increased serum insulin concentration and insulin resistance index; however, it did not improve serum CRP concentration in high-fat diet fed rats." (PMID 32172503, 2020). "We evaluated: fasting plasma glucose (FPG), postprandial plasma glucose (PPG), glycated hemoglobin (HbA1c), fasting plasma insulin (FPI), homeostatic model assessment of insulin resistance (HOMA-IR), lipid profile and high sensitivity C-reactive protein (Hs-CRP)." (PMID 32987917, 2020). "Moreover, it hindered insulin resistance, LVH, and ventricular inflammatory process, as indicated by the lower expression of CD40L and lower serum CRP levels." (PMID 32881885, 2020). "High levels of CRP are also involved in the production of adhesion molecules, namely, E-selectin, ICAM-1, and VCAM-1, which play a role in vascular endothelial dysfunction, insulin transport reduction, and peripheral insulin resistance." (PMID 31485456, 2019). "In our study, serum CRP concentrations were highly correlated with HOMA-IR values and were the only significant predictor of insulin resistance in the regression analysis, suggesting a possible role for inflammation in the development of insulin resistance in psoriasis." (PMID 30735527, 2019). "Previous studies suggest that several cytokines and inflammatory mediators in the plasma are up-regulated in insulin resistance, including tumor necrosis factor-α (TNF-α), monocyte chemotactic protein-1 (MCP-1), C-reactive protein (CRP), and interleukin-6 (IL-6)." (PMID 31035653, 2019). "In previous observational studies, more sedentary time was associated with increased maternal leptin, lipid levels and C-reactive protein levels but not with insulin resistance or glucose." (PMID 30840112, 2019). "Subjects with insulin resistance had a higher concentration of hs-CRP (p = 0.002) and IL-6 (p = 0.002) than subjects without insulin resistance." (PMID 29466985, 2018). "Neither LPC 15:0 and LPC 17:0 species was associated with insulin resistance but LPC 14:0 and the overall LPC class were associated with CRP at our pre-determined p < 0.01 level." (PMID 28817063, 2017). "The effects of salsalate on the parameters of insulin resistance were different in the presence of CRP-induced inflammation versus in the absence of inflammation." (PMID 28586387, 2017).
Insulin resistance (continued). "However, once insulin resistance arises, the inflammatory pathways are activated, and the levels of IL-6, IL-8, TNF-α, and CRP increase significantly and produce different degrees of injury in the body." (PMID 27187341, 2016). "Patients with type 2 DM and MetS showed significantly higher blood CRP and insulin resistance than type 2 DM without MetS." (PMID 28042581, 2016). "Several prospective studies show high sensitivity-CRP (hs-CRP) levels are a good predictor of the future advancement of type 2 diabetes in nondiabetic individuals regardless of fat distribution and insulin resistance." (PMID 28003714, 2016). "In the context of CRP and CVD, it is worthy of note that CRP predicted risk after adjustments for traditional and metabolic risk factor, including estimates of insulin resistance and HgA1c, and that CRP also predicted CVD in the non-smoking part of Inter99." (PMID 26035431, 2015). "An initial report has been published showing that metformin significantly improved metabolic parameters such as weight, insulin, glucose, leptin, and C-reactive protein (CRP) at 6 months, regardless of initial weight or degree of insulin resistance." (PMID 26111812, 2015). "Moreover, we studied the association of vitamin D concentrations with anthropometric characteristics, lipoprotein parameters, C-reactive protein (CRP) and insulin resistance and analysed the effects of lipid-lowering treatment." (PMID 24450309, 2014). "An inverse trend across all PI/I quartiles was noted for BMI and serum levels of total cholesterol (T-C), LDL-C, HDL-C and C reactive protein (CRP), and with homeostatic model assessment (HOMA-B) and HOMA of insulin resistance (HOMA-IR) values (P<0.05 for all)." (PMID 25347846, 2014). "Increased levels of high sensitivity C-reactive protein (hs-CRP) and plasminogen activator inhibitor type-1 (PAI-1) are associated with insulin resistance rather than impaired pancreatic β-cell function in prediabetic individuals." (PMID 24772446, 2014). "A possible link exist between decreased adiponectin with increased insulin resistance, while some evidence links increased TNF-α and resistin with increased insulin resistance Another study relate higher blood pressures to decreased adiponectin, increased TNF-α, and CRP concentrations." (PMID 24571954, 2014). "Furthermore, there was correlation with testosterone (r=−0.306, P<0.01) and other androgens, homeostasis model of assessment insulin resistance (HOMA IR; r=0.456, P<0.001), VO2 max (r=−0.262, P=0.04), IGF1 (r=−0.297, P=0.01), and CRP (r=0.302, P=0.01)." (PMID 24148221, 2013). "The reductions in DAS28-CRP, CRP and IL-6 levels were independent of improvement in insulin resistance." (PMID 24020899, 2013). "In another study as well, prominent expression of the LCN2 protein was found in the visceral adipocytes of obese patients (with insulin resistance and elevated high-sensitivity CRP but without apparent liver injury)." (PMID 23875831, 2013). "High levels of CRP are not recommended in subjects with type 1 diabetes because they can increase insulin resistance and they can also exacerbate ongoing inflammatory processes in the blood vessels accelerating the progression of diabetic complications." (PMID 22322513, 2012). "Other top predictors included markers of insulin resistance and the IGF pathway (insulin, IGFBP1, uric acid), sex hormones (free estradiol, SHBG), lipid-soluble micronutrients (vitamin D3, lycopene, CoQ10, alpha-tocopherol) and markers of inflammation (CRP)." (PMID 22912885, 2012). "This inverse association between serum testosterone and NAFLD persisted even after controlling for the effect of VAT, insulin resistance (as HOMA-IR), and low-grade inflammation (as hs-CRP), which are considered as possible links between testosterone and NAFLD." (PMID 22691278, 2012).
Insulin resistance (continued). "Evaluate the effect of physical training on BMI, lipid profile, CRP, leptin and insulin resistance among obese Egyptian children with and without metabolic syndrome." (PMID 22691465, 2012). "Anti-TNF treatment reduced DAS28 (P = 0.007), HAQ (P = 0.002), and CRP (P = 0.002) in patients with insulin resistance but not in those with HOMA-IR ≤ 2.0 (data not shown)." (PMID 22691241, 2012). "This inverse association was independent of the effect of VAT, insulin resistance (as HOMA-IR), and low-grade inflammation (as hs-CRP)." (PMID 22691278, 2012). "Although obese adolescents had clear evidence of insulin resistance, only CRP, fibrinogen and leptin were elevated; there were no group differences in pro- or anti-inflammatory cytokines nor adiponectin and resistin." (PMID 22682228, 2012). "In the Insulin Resistance Atherosclerosis Study, the addition of CRP to a prediction model for type 2 diabetes that was based on the metabolic syndrome (without or with an estimate of insulin resistance) had little impact on AUCs." (PMID 21674000, 2011). "Homeostasis model assessment of insulin resistance (HOMA-IR), HOMA-B, plasma concentrations of C-peptide, CRP, fatty acid composition and the GCKR rs1260326-P446L polymorphism, were determined in a cross-sectional analysis of 379 subjects with MetS participating in the LIPGENE dietary cohort." (PMID 21674002, 2011). "Insulin resistance and C-reactive protein were not estimated in this study in order to reduce costs; however these would not have affected the outcome of our study objectives." (PMID 20224842, 2010). "These associations were no longer significant after adjustment for insulin resistance and C-reactive protein." (PMID 21143922, 2010). "Serum C-reactive protein and fibrinogen as well as spleen longitudinal diameter were significantly increased in the obese young with insulin resistance compared to non-insulin resistance group." (PMID 19291292, 2009). "When patients were divided into two groups according to presence of insulin resistance, insulin resistance did not affect the CRP and PCT levels in NAFLD patients." (PMID 19222849, 2009). "Recent studies have associated LEPR gene variants with inflammatory traits like plasma fibrinogen and C-reactive protein levels, bone density and insulin resistance in nondiabetic obese patients." (PMID 19562039, 2009). "Of forty two young individuals, divided into two groups (with or without insulin resistance), were studied serum C-reactive protein and fibrinogen as indexes of chronic pro-inflammatory status." (PMID 19291292, 2009). "These authors found that the link between adiponectin levels and a strong marker of inflammation, CRP, is independent of insulin resistance and adiposity in obese children and adolescents." (PMID 21274300, 2009). "However, adiponectin secretion is known to be influenced by factors that induce insulin resistance, which include tumor necrosis factor (TNF)-α, interleukin (IL)-6, C-reactive protein (CRP), lipid metabolism, diet and exercise habits." (PMID 18507868, 2008). "Furthermore, insulin resistance, a crucial metabolic marker associated with NAFLD progression, and high-sensitivity C-reactive protein (Hs-CRP), an essential indicator of systemic inflammation, were not assessed." (PMID 40951429, 2025). "Furthermore, Louis established a negative correlation between Subdoligranulum abundance and CRP levels, as well as the Homeostasis Model Assessment of Insulin Resistance (HOMA-IR)." (PMID 40565024, 2025). "As for type 1 diabetes, there is no clear-cut report of HbA1c reduction by periodontal treatment, and it is classically known that elevated inflammatory markers such as CRP are related to insulin resistance (HOMA-IR) rather than insulin secretion capacity (HOIMA-β)." (PMID 40070580, 2025).